AHR (aryl hydrocarbon receptor)
Diseases named in the same sentence as AHR in open-access papers (continued):
Sharing a sentence is not in itself a finding about the gene and the disease.
neuroblastoma (34 papers, 2006 to 2024). Neuroblastoma (NB) is the most common solid, extracranial childhood tumor. "Similar results were reported by other teams where overexpression of AhR caused neural differentiation of Neuro2a cells, and high expression of AhR was observed in samples from human neuroblastoma cells." (PMID 34342853, 2021). "Our group previously identified clofazimine (CLF), an FDA-approved antibiotic approved for drug-resistant tuberculosis and lepromatous leprosy, as a novel AhR antagonist with anti-multiple myeloma and anti-neuroblastoma efficacy." (PMID 38807762, 2024). "Recent work from our laboratory suggests AhR acts as a tumor promoter in MYCN-amplified neuroblastoma." (PMID 38807762, 2024). "For instance, while kynurenine signaling has been dominantly characterized by its role in immune suppression, kynurenine was also found to have tumor-suppressive effects downstream of AhR in neuroblastoma, driving cellular differentiation." (PMID 37106727, 2023). "The expression of AhR is inversely correlated with the expression of the neuroblastoma driver MYCN, and the overexpression or activation of AhR by the endogenous metabolite kynurenine inhibited the growth of xenografts." (PMID 37106727, 2023). "As an example, AHR and MYCN expression were demonstrated to be inversely correlated in neuroblastoma, with an AhR staining correlated with tumor differentiation and favorable patient outcome." (PMID 35681770, 2022). "This is of interest, because TCDD exposure has been reported to reduce acetylcholine esterase (AChE) activity in an AhR-dependent fashion in cholinergic neurons derived from a human neuroblastoma cell line, SK-N-SH." (PMID 35890127, 2022). "In childhood neuroblastoma, AhR plays a protective role, as its expression correlates with a better outcome." (PMID 33451095, 2021). "Aryl hydrocarbon receptor is a ligand-dependent transcription factor which has been reported to have connections with tumor metastasis of thyroid carcinoma, neuroblastoma and inflammatory breast cancer." (PMID 32546278, 2020). "Further, kynurenine-mediated activation of AHR impaired tumor progression and metastasis in a neuroblastoma model." (PMID 33214553, 2020). "Although the dominant interpretation of the immunomodulatory effect of activated AhR is immunosuppression, in pituitary adenomas and neuroblastomas, on the contrary, activation of the antitumor immune response through AhR-dependent mechanisms is observed." (PMID 32325928, 2020). "Overexpression of constitutively active AhR in transgenic mice models has been reported to induce gastric and hepatocellular cancer, whereas decreased AhR activity promotes neuroblastoma metastasis." (PMID 32988402, 2020). "This is supported by the finding that CDC42 expression was increased through over-expression of AhR in mouse Neuro2a neuroblastoma cells." (PMID 28860601, 2017). "Similar results were also obtained in neuroblastoma, where ectopic expression of AHR was found to downregulate MYCN (specific malignant factor of neuroblastoma) and E2F1 expression and correlated highly with the histological grade of differentiation." (PMID 27752740, 2017). "DAC treatment increased substantially AHR mRNA level, suggesting for the first time that AHR silencing relies on DNA methylation in this neuroblastoma model." (PMID 27006469, 2016). "Gene expression analysis identified MYCN as a novel AhR target gene repressed in neuroblastoma cells by a mechanism involving the transcription factor E2F1." (PMID 27243009, 2016). "To analyze the relationship between AhR activation and neurotoxicity in a previous study, we stably transfected cells of the murine neuroblastoma cell line, Neuro2a, with AhR cDNA to produce N2a-R cells." (PMID 19500377, 2009). "The murine neuroblastoma cell line, Neuro2a, was transfected with AhR cDNA in the expression vector (pcDNA4/V5-His), which includes the V5 epitope and the cytomegalovirus promoter." (PMID 16956419, 2006).
neuroblastoma (continued). "In the present study, we transfected a neuroblastoma cell line, Neuro2a, with cloned AhR and examined the effect of over-expression of the AhR on these cells." (PMID 16956419, 2006). "The undifferentiated murine neuroblastoma Neuro2a cell line (ATCC) was stably transfected with AhR cDNA and the established cell line was named N2a-Rα." (PMID 16956419, 2006). "The complete inhibition of CYP1A1 induction in neuroblastoma cells and cyp1a in zebrafish by the AHR antagonist GNF-351 strongly supports the hypothesis that AHR activation is instrumental for EDA-induced CYP pathway stimulation." (PMID 38672460, 2024). "The next step involved the evaluation of EDA as a novel AHR agonist by docking and molecular dynamics simulations using an AHR 3D structure, the analysis of AHR nuclear translocation and AHR target gene expression in the human neuroblastoma cell line SH-SY5Y and zebrafish larvae." (PMID 38672460, 2024). "This notion was further supported by the facts that enforced expression of AHR suppresses neuroblastoma progression in vivo and kynurenine, an endogenous agonist of AHR derived from tryptophan metabolism 56, inhibits proliferation and promotes differentiation of the neuroblastoma cells." (PMID 37151890, 2023). "In neuroblastoma, AhR has been shown to inhibit tumors’ growth and metastasis." (PMID 37106727, 2023). "miR-124 plays a pivotal role in neuroblastoma by targeting AHR, which may promote neuroblastoma cell differentiation." (PMID 26041995, 2015). "Because kynurenine (Kyn), a tryptophan catabolite was recently identified as an endogenous ligand of AhR in neuroblastoma, we attempted to define the relevance of the AhR regulation of KYNU, which is the enzyme downstream of the implicated AhR endogenous ligand, Kyn." (PMID 24932473, 2014). "N2a-Rβ cells were established by transfecting murine neuroblastoma Neuro2a with the rat AhR cDNA." (PMID 19500377, 2009). "Thus, current evidence lends support to the hypothesis that AhR has a dual tumor modulatory role depending on the neuroblastoma subtype." (PMID 38807762, 2024). "Experimental findings confirm that miR-124 may affect neuroblastoma cell differentiation by targeting AhR, promotes the intestinal inflammation in Crohn’s disease, and regulates cellular inflammatory response through negatively regulating AhR expression in chronic rhinosinusitis." (PMID 34281170, 2021). "Therefore, we hypothesize that transcriptional up-regulation via AhR pathway might participate the dioxin-mediated CDC42 induction in the present human neuroblastoma cells." (PMID 28860601, 2017). "Using targeted transcriptomic analysis and qPCR, we observed a significant increase in the expression of genes related to the AHR pathway (CYP1A1, CYP1B1, AHRR) in mouse OPCs and human neuroblastoma SH-SY5Y cells after treatment with EDA." (PMID 38672460, 2024). "The top score was obtained for AHR (Aryl Hydrocarbon Receptor) signaling pathway, which is inversely correlated to MYCN expression in neuroblastoma tissue." (PMID 36793342, 2022). "We have found that AhR transcriptional activity correlates with poor patient prognosis, positively regulates MycN, and represses differentiation of MYCN-amplified neuroblastoma cells by altering chromatin accessibility and modulating the retinoic acid receptor pathway." (PMID 38807762, 2024). "We and others have also reported that AhR has a tumor suppressive role in non-MYCN-amplified neuroblastoma cells." (PMID 38807762, 2024). "Treatment of non-MYCN-amplified neuroblastoma cells with TCDD has been found to induce non-apoptotic cell death via an AhR-dependent mechanism." (PMID 38807762, 2024). "It was found that in the absence of miR-124 in SK-N-SH neuroblastoma cells, AhR protein expression increases while cell proliferation slows and the cell cycle is blocked." (PMID 32325928, 2020).
neuroblastoma (continued). "The most relevant reports on AHR- and CAR-regulated miRNA showed the inversely co-related expression of AIP (AHR-interacting protein) and miR-107 in pituitary adenomas, as well as CAR and miR-137 in neuroblastoma cells." (PMID 29137141, 2017). "The comparative analysis of neuroblastoma tumors having or lacking amplification of the prognostic MYCN marker revealed that AhR expression was inversely correlated with MYCN amplification and, importantly, with an increased grade of tumor differentiation." (PMID 27243009, 2016). "To attempt to generalize our results, we analyzed AHR mRNA levels in neuroblastoma SH-SY5Y cells, another model lacking AHR expression." (PMID 27006469, 2016). "Therefore, we attempted to analyze the participation of AhR activation following exposure of the developing neuron to TCDD, by producing and using N2a-Rα cells, which were stably transfected with AhR cDNA in an undifferentiated neuroblastoma cell line, Neuro2a." (PMID 16956419, 2006). "We also found that AHR mRNA levels were increased by DAC and Iso-3 in neuroblastoma SH-SY5Y cells, in which AHR is known to be absent by so far non-described mechanisms." (PMID 27006469, 2016).
Crohn disease (32 papers, 2014 to 2025). A gastrointestinal disorder characterized by chronic inflammation involving all layers of the intestinal wall, noncaseating granulomas affecting the intestinal wall and regional lymph nodes, and transmural fibrosis. "Similarly, AhR expression is downregulated in inflammatory bowel conditions, including Crohn disease, whereas AhR activation is associated with inhibition of intestinal inflammatory responses." (PMID 40663393, 2025). "Activation of AhR by Tetrachlorodibenzo-p-dioxin (TCDD) has been shown to alleviate intestinal inflammation in Crohn’s disease." (PMID 41031160, 2025). "Intestinal T cells isolated from Crohn’s disease patients have decreased levels of AHR, but upon exposure to AHR, ligands downregulate inflammatory cytokines and upregulate IL-22." (PMID 39242971, 2024). "Activation of AHR can augment the production of IL‐22, an inflammatory cytokine, causing cutaneous inflammation, PCOS, or Crohn's disease." (PMID 38468402, 2024). "Compared to healthy ones, AHR expression was decreased in the inflammatory tissues of Crohn’s disease patients, and the amount of natural AHR ligands was significantly lower in the feces of ulcerative colitis patients." (PMID 37179416, 2023). "Expression of the AhR gene is reduced in the intestine of patients with Crohn’s disease; additionally, IBD patients produce fewer AhR agonists." (PMID 37110329, 2023). "MiR-124 has been implicated in induction of intestinal inflammation through the inhibition of the AhR; therefore, initiating key events in the pathogenesis of Crohn’s disease." (PMID 35626744, 2022). "Analysis of SAhRMs identified nine small molecules that modulated the AhR and three in development for Crohn’s disease." (PMID 35626744, 2022). "Our previous studies revealed that Th17 cells obtained from patients with Crohn’s disease are poorly responsive to AhR activation by UCB, as demonstrated by failure to undergo regulation and acquire immunosuppressive properties." (PMID 36131123, 2022). "Most recently, researchers employing AHR knockout mouse models have also uncovered a role for the AHR in Crohn’s disease and adenine-driven kidney disease." (PMID 33374508, 2020). "In vitro exposure of Tregs and Th17 cells to APT102 boosts the effects of AhR stimulation in Crohn's disease patients' samples, as reflected by increased CD39, FOXP3, and LAG-3 levels in these cells." (PMID 33553158, 2020). "In Crohn’s disease, AhR RNA transcripts were markedly downregulated in the inflamed tissue and in the CD4 + T cells." (PMID 32764642, 2020). "AhR is newly reported to improve immune homeostasis in diseases related to excessive proinflammatory status, such as Crohn's disease." (PMID 31691738, 2019). "Overall, these results are in agreement with data of previous studies showing that AhR activation reduces the production of inflammatory cytokines in mucosal cells of Crohn's disease patients and murine models of intestinal inflammation." (PMID 30778350, 2019). "In the context of HS, AhR activation may promote the expansion of Th17 cells, which are involved in chronic inflammatory conditions like Crohn’s disease." (PMID 40472049, 2025). "Future studies should determine whether PPARα, PPARγ, AMPK, and mTOR modulate glycolysis in Crohn’s disease in an AhR-independent manner." (PMID 36131123, 2022). "Furthermore, in Crohn's disease, Th17 cells display defective response to AhR activation via UCB, this being reflected by inadequate upregulation of CD39." (PMID 33553158, 2020). "For instance, on the one hand, Crohn’s disease (CD) and ulcerative colitis (UC) are characterized by a reduced AhR pathway, and AhR agonists or AhR-activating probiotics might be beneficial." (PMID 32823705, 2020). "Therefore, it is conceivable that AhR can be down-regulated by either inflammatory molecules (e.g., IL-15 and Th1 cytokines), which are over-produced in both CD and Crohn's disease, or factors that are differently synthesized in the two disorders." (PMID 30778350, 2019).
Crohn disease (continued). "We have previously shown that UCB serves as AhR endogenous ligand and confers immunosuppressive properties to Th17 cells obtained from healthy controls, whereas these properties are impaired in Th17 cells derived from the peripheral blood and lamina propria of Crohn’s disease patients." (PMID 36131123, 2022). "Therefore, blockade of PGK1 or ALDOA should be considered as a potential immunotherapeutic strategy to boost AhR activation and ultimately control Th17 cell inflammatory potential while favoring the acquisition of suppressive features by these cells in Crohn’s disease." (PMID 36131123, 2022). "AhR regulates the differentiation of Th17 and Treg cells; therefore, the difference in its expression shifts the balance between these two T cell subtypes and may contribute to the pathogenesis, among others, of Crohn’s diseases (CD)." (PMID 32899152, 2020). "Additionally, activation of AhR may modulate immune and inflammatory responses, so studying the effects of AhR activation on the pathogenesis of Crohn’s disease is warranted." (PMID 24905409, 2014). "In Crohn’s disease, however, Th17-cells display lower AhR expression and higher levels of hypoxia-inducible-factor-1alpha (HIF-1α), known to inhibit AhR levels and signaling." (PMID 30691212, 2019). "In Crohn’s disease, the altered response of Th17 cells to UCB also derives from high levels of HIF-1α that, in concert with a hypoxic environment, limits the responsiveness of these cells to AhR activation." (PMID 36131123, 2022). "Although these data would seem to suggest a direct and negative effect of dietary gluten on AhR, we have previously documented a diminished expression of AhR in Crohn's disease, another chronic inflammatory disorder of the gut, which is not driven by gluten." (PMID 30778350, 2019).
multiple sclerosis (31 papers, 2017 to 2026). A progressive autoimmune disorder affecting the central nervous system resulting in demyelination. "In particular, the risk of multiple sclerosis correlates with smoking, which drives AhR gene demethylation and inhibits AhR signaling pathways, followed by the enhancement of inflammatory processes in the central nervous system in multiple sclerosis." (PMID 35743162, 2022). "Overall, our study first reports the role of the AhR in the pathogenesis of demyelinating diseases associated with inflammation such as optic neuritis or multiple sclerosis, providing new avenues for the understanding and the treatment of nystagmus-related pathologies." (PMID 28851966, 2017). "The role of AhR in astrocyte-driven inflammation has been documented in experimental mouse models of multiple sclerosis." (PMID 41254302, 2025). "Previous study on multiple sclerosis mouse model showed that AHR acts as a negative regulator of NF-κB activation." (PMID 38962126, 2024). "Pharmacological Modulation of AhR and NFkB with Dimethyl fumarate in Vitamin-D3-Tolerogenic Dendritic Cells derived from multiple sclerosis patients restores their properties, providing a promising combined therapy." (PMID 39287981, 2024). "Patients with multiple sclerosis have lower levels of circulating AhR than healthy controls do, suggesting that AhR is involved in the pathogenesis of this disorder." (PMID 35743162, 2022). "In multiple sclerosis, the gut microbiome is altered, which represents an interesting opportunity for investigating the role of the kynurenine–AhR pathway in this pathology." (PMID 35743162, 2022). "Multiple sclerosis (MS) is a demyelinating disease of the central nervous system, in which AhR also plays an active role." (PMID 36110860, 2022). "Concentrations of AhR in plasma are decreased in patients with multiple sclerosis, with AhR activity changing in response to disease activity." (PMID 31096592, 2019). "We compared different reporter systems for the detection of AHR agonists in serum samples of Multiple Sclerosis (MS) patients, and assessed the influence of transfection methods and cell lines in a reporter-based in vitro assay." (PMID 29563571, 2018). "Rothhammer and colleagues found that gut-derived metabolites of dietary tryptophan limit astrocyte inflammatory activity directly through aryl hydrocarbon receptor mediated IFN-I signaling in the experimental autoimmune encephalitis (EAE) model of Multiple Sclerosis." (PMID 37415149, 2023). "AhR may limit the central nervous system-inflammation characteristic of multiple sclerosis by suppressing astrocyte activation." (PMID 35743162, 2022). "Furthermore, in an animal model of multiple sclerosis (autoimmune encephalomyelitis), treatment with laquinimod, which crosses the blood–brain barrier, reduces astrogliosis and prevents the production of downstream proinflammatory cytokines in an AhR-dependent manner." (PMID 35743162, 2022). "However, dysregulation of this feedback loop allows uncontrolled AhR activation, which is correlated with inflammatory processes including IBD, multiple sclerosis, cardiovascular conditions, and allergic responses, and carcinogenesis." (PMID 33916690, 2021).